MPZL3 (myelin protein zero like 3)
Description:
Mediates homophilic cell-cell adhesion.
Tractability: Antibody: UniProt predicts a signal peptide or a membrane-spanning region; its Gene Ontology location is reachable by antibodies, with medium confidence.
Gene: Protein-coding gene on chromosome 11 (118,226,690 to 118,252,365, reverse strand). Ensembl gene ENSG00000160588.
Subcellular location: Membrane
Subcellular location (Human Protein Atlas): Golgi apparatus
Gene Ontology:
Molecular function: protein binding
Cellular component: plasma membrane; membrane
Genetic constraint (gnomAD): Loss-of-function variants: 17 observed, 21.69 expected, observed/expected ratio (o/e) 0.78, 90% interval 0.54 to 1.18. The upper end of that interval is the gene's LOEUF score, 1.18, which puts it in group 5 of 6, group 1 being the genes least tolerant of losing a copy. Missense variants: 252 observed, 269.38 expected, observed/expected ratio (o/e) 0.94, 90% interval 0.84 to 1.04. Synonymous variants: 88 observed, 99.9 expected, observed/expected ratio (o/e) 0.88, 90% interval 0.74 to 1.05.
Homologues: Orthologues: chimpanzee MPZL3 (99% identical), dog MPZL3 (90% identical), pig MPZL3 (88% identical), mouse Mpzl3 (88% identical), guinea pig MPZL3 (85% identical), rat Mpzl3 (83% identical), rabbit MPZL3 (79% identical), tropical clawed frog mpzl3 (44% identical). Paralogues in human: MPZL1 (27% identical), MPZ (26% identical), MPZL2 (24% identical), SCN2B (20% identical), SCN4B (20% identical), JAML (18% identical).
Diseases named in the same sentence as MPZL3 in open-access papers:
MPZL3 is named in the same sentence as 32 diseases in open-access papers, as found by Europe PMC text mining. Sharing a sentence is not in itself a finding about the gene and the disease. The quoted sentences say what the papers report.
rectal cancer (4 papers, 2018 to 2022). A primary or metastatic malignant neoplasm that affects the rectum. "More recently, MPZL3 has been identified as a radio-resistant candidate marker gene in rectal cancer cell lines." (PMID 35249128, 2022). "MPZL3 mRNA has been reported to be highly expressed in radioresistant rectal cancer cell lines." (PMID 35965540, 2022). "A microarray analysis indicated the RNA expression of five genes (NDRG1, ERRFI1, H19, MPZL3, and UCA1) was highly increased in radio-resistant rectal cancer cell lines." (PMID 29801473, 2018).
alopecia (3 papers, 2020 to 2022). Hair loss usually from the scalp. "Polymorphism and mutation analyses of MPZL3 gene expression indicated the possibility that homozygous or compound heterozygous mutations of MPZL3 are related to immune-mediated hereditary hair loss." (PMID 35965540, 2022). "Interestingly, loss of MPZL3 function has also been shown to cause various skin abnormalities including sebaceous gland hypertrophy and progressive cyclic alopecia." (PMID 33991450, 2021). "Interestingly, depletion of the myelin protein zero-like 3 (MPZL3) is associated with dermatitis and alopecia in mice, and the ETC enzyme ferredoxin reductase (FDXR) sensitizes various human epithelial cell lines to ROS-induced apoptosis." (PMID 32518230, 2020). "Thus, increased energy expenditure and overall reduction in lipids in Mpzl3 KO mice may be compensatory to alopecia, rather than reflective of direct effects of Mpzl3 loss on systemically regulated metabolic changes." (PMID 33991450, 2021). "We report that in the absence of alopecia, Mpzl3 ASO‐mediated knockdown effectively recapitulated several of the phenotypes observed in global Mpzl3 KO mice fed HED." (PMID 33991450, 2021).
dermatitis (3 papers, 2019 to 2022). An inflammatory process affecting the skin. "It has been found the abnormal function of Mpzl3 involves a skin disorder." (PMID 36316632, 2022).
lung carcinoma (3 papers, 2022 to 2025). "Abnormal expression of MPZL3 is involved in the development of lung carcinoma." (PMID 40584831, 2025).
breast carcinoma (2 papers, 2022 to 2025). "High MPZL3 expression has been associated with poor prognosis in breast cancer and shown to drive the proliferation of MET-amplified cancer cell lines." (PMID 40631617, 2025). "Overall, high MPZL3 expression was linked to poor prognosis across cancers, including breast cancer." (PMID 35965540, 2022). "Whereas this chromosomal region has been reported to be lost in many cancers, suggesting a tumor-suppressor function for MPZL3, previously published bioinformatics data have suggested that MPZL3 is a prognostic marker in breast cancer." (PMID 40631617, 2025). "In a gene expression profile analysis of breast cancer, MPZL3 was one of the significantly downregulated genes in premalignant adjacent tissues compared with the corresponding tumor tissues." (PMID 35965540, 2022). "This study provides a comprehensive analysis and understanding of the oncogenic roles of the pan-cancer gene MPZL3 across different tumors, including breast cancer." (PMID 35965540, 2022). "To investigate the role of MPZL3 in breast cancer (BC), we first constructed BC cell lines with stable transduction and high expression of MPZL3." (PMID 35965540, 2022). "To analyze the role of MPZL3 in different subtypes of breast cancer, we first constructed MPZL3-overexpressing cell lines." (PMID 35965540, 2022). "Furthermore, we validated the role of MPZL3 in cell proliferation and drug sensitivity in different molecular subtypes of breast cancer cells." (PMID 35965540, 2022). "It was found that MPZL3 can promote proliferation in breast cancer cell lines." (PMID 35965540, 2022). "In addition, in breast cancer, we identified that MPZL3 is capable of promoting breast cancer cell proliferation and exerts an essential influence on drug therapeutic options, suggesting that MPZL3 serves as a potential prognostic biomarker for breast cancer." (PMID 35965540, 2022). "MPZL3 could be a potential prognostic biomarker and therapeutic target for breast cancer." (PMID 35965540, 2022). "Furthermore, drug sensitivity analysis and validation in breast cancer also indicate that MPZL3 might be a potential target for anticancer therapy." (PMID 35965540, 2022). "A closely related homolog of MPZL3, MPZL2 (EVA1) localizes with E-cadherin and ZO-1 at cell–cell junctions in breast cancer epithelial cells." (PMID 40631617, 2025). "Therefore, we hypothesized that MPZL3 could mediate immune functions in breast cancer." (PMID 35965540, 2022).
cutaneous squamous cell carcinoma (2 papers, 2022). "While MPZL3 has been reported to act as a tumor suppressor in cutaneous squamous cell carcinoma through its activity promoting differentiation, our proliferation and colony-forming assays demonstrate an oncogenic role for MPZL3 in lung and gastric carcinoma cells." (PMID 35249128, 2022).
gastric cancer (2 papers, 2022). A primary or metastatic malignant neoplasm involving the stomach. "We discovered that MPZL3 mRNA is significantly increased in gastric cancer when compared to normal gastric tissues." (PMID 35249128, 2022). "Accordingly, MET gene amplification predicted higher MPZL3 expression than cell lines without any RTK amplification and MPZL3 levels are positively correlated with MET and ERBB3 expression in LUSC and gastric carcinomas." (PMID 35249128, 2022).
ovarian carcinoma (2 papers, 2019 to 2025). A malignant neoplasm originating from the surface ovarian epithelium. "Our study suggests that decreased expression of the predicted adhesion molecule MPZL3 is associated with low proliferation but increased metastatic potential during ovarian cancer tumor progression." (PMID 40631617, 2025). "It remains to be determined how this interpatient heterogeneity related to MPZL3 locus gain and loss reflects on MPZL3 expression levels during different stages of ovarian cancer initiation, progression, and metastasis." (PMID 40631617, 2025). "In this study, we set out to explore the role of MPZL3 in ovarian cancer and found that loss of MPZL3 results in loss of homotypic cell adhesion and a more invasive phenotype associated with epithelial to mesenchymal transition (EMT)." (PMID 40631617, 2025). "Moreover, VIM expression was inversely correlated to MPZL3 expression in TCGA ovarian cancer specimens, indicating that decreased MPZL3 expression is associated with upregulation of the canonical EMT gene VIM in ovarian cancer." (PMID 40631617, 2025). "Further studies are needed to determine whether loss of MPZL3 similarly affects lipid metabolism in ovarian cancer cells." (PMID 40631617, 2025). "Interestingly, the MPZL3 locus (11q23.3) is susceptible to chromosomal loss in multiple cancer subtypes, and loss of heterozygosity of this location is a frequent event in ovarian cancer." (PMID 40631617, 2025). "In summary, our findings demonstrate that loss of MPZL3 induces EMT, reduces homotypic cell adhesion, and promotes invasion of ovarian cancer cells." (PMID 40631617, 2025). "We addressed this in ovarian cancer, in which both MPZL3 amplification and deletions are observed in respective subsets of high-grade serous specimens." (PMID 40631617, 2025). "We found a similar percentage of chromosome gains and losses at the MPZL3 locus in the TCGA ovarian adenocarcinoma dataset, leading us to question how MPZL3 influences ovarian cancer development and progression." (PMID 40631617, 2025). "This work presents novel findings that decreased expression of the potential cell adhesion molecule MPZL3 is a phenotype of ovarian cancer progression and metastasis." (PMID 40631617, 2025). "In this study, we investigated the role of MPZL3 in ovarian cancer." (PMID 40631617, 2025). "From our unbiased RNA-seq analysis performed on two ovarian cancer cell lines following MPZL3 knockdown, we observed that EMT gene sets were the most significantly enriched in the knockdown group, and that cell proliferation and cell-cycle gene sets were predominantly expressed in the control group." (PMID 40631617, 2025). "Loss of MPZL3 decreased homotypic adhesion between ovarian cancer cells but did not affect heterotypic cell adhesion to mesothelial cells, suggesting that MPZL3 shares functional similarities to junctional adhesion molecules such as VSIG1." (PMID 40631617, 2025). "Thus, our data suggest that decreased MPZL3 expression may be a phenotype of ovarian cancer tumor progression and metastasis." (PMID 40631617, 2025). "To determine whether MPZL3 has CAM properties in ovarian cancer cells, we tested the effects of MPZL3 knockdown in OVCAR4 cells on homotypic cell adhesion by quantifying their attachment to a monolayer of parental OVCAR4 cells, and assessing their heterotypic adhesion to mesothelial cells." (PMID 40631617, 2025).
breast invasive carcinoma (1 paper, 2024). "A positive correlation was identified between the infiltration of CD8+ T cells, CD4+ T immune cells, B cells, and other immune cells, and the expression of MPZL3 in breast invasive carcinoma (BRCA)." (PMID 39290707, 2024).
dyslipidemia (1 paper, 2021). "Inhibiting MPZL3 could be a potential therapeutic approach for the treatment of obesity and associated dyslipidemia." (PMID 33991450, 2021).
gastric adenocarcinoma (1 paper, 2022).
gastric tumors (1 paper, 2022). "We found that MPZL3 expression is positively correlated with MET and ERBB3 expression in gastric tumors and in LUSC." (PMID 35249128, 2022).
Glucose intolerance (1 paper, 2021). Glucose intolerance (GI) can be defined as dysglycemia that comprises both prediabetes and diabetes. "Mpzl3 ASOprevented the body weight gain, increase in adiposity, glucose intolerance andhyperlipidemia typically associated with exposure to a high‐fat and sucrose, energy‐dense diet." (PMID 33991450, 2021). "Mpzl3 ASO prevented the BW gain, increase in adiposity, glucose intolerance and hyperlipidemia typically associated with HED intake." (PMID 33991450, 2021).
Hyperglycemia (1 paper, 2021). An increased concentration of glucose in the blood. "We previously showed that Mpzl3 global KO mice have increased energy expenditure and resistance to the negative effects of HED, including weight gain, hyperlipidemia and hyperglycemia." (PMID 33991450, 2021). "While increasing mitochondrial fatty acid oxidation alone may not reduce adiposity, the tissue specific effects we observed in Mpzl3 ASO‐treated mice could have cumulatively led to protection against the weight gain, hyperlipidemia and hyperglycemia normally seen in mice fed HED." (PMID 33991450, 2021).
hyperlipidemia (1 paper, 2021). "Together, these data demonstrate that Mpzl3 inhibition is a potential therapeutic approach for treatment of obesity and related comorbid conditions, including insulin resistance, hyperlipidemia and cardiovascular dysfunction." (PMID 33991450, 2021).
immunodeficiencies (1 paper, 2024). "Moreover, mutations in the conserved V-type domain of MPZL3 can impact immune function, potentially leading to immunodeficiencies." (PMID 39290707, 2024).
lung adenocarcinoma (1 paper, 2024). A carcinoma that arises from the lung and is characterized by the presence of malignant glandular epithelial cells. "There were 5 genes with a causal relationship to lung adenocarcinoma, including RNASET2, MPZL2, MPZL3, CHRNA5 and UCKL1." (PMID 38834983, 2024).
lung squamous cell carcinomas (1 paper, 2022). "To further investigate the relevance of Met and HER3 in MPZL3 regulation, we examined available datasets of gastric and lung squamous cell carcinomas (LUSC)." (PMID 35249128, 2022).
metastatic disease (1 paper, 2025). "This suggests that MPZL3 loss may be a feature of tumor progression and metastatic disease." (PMID 40631617, 2025).
Obesity (1 paper, 2021). Accumulation of substantial excess body fat. "Unexpectedly, Pck1, a main control point for gluconeogenesis that has been linked to diabetes and obesity, was significantly upregulated in livers of Mpzl3 ASO animals." (PMID 33991450, 2021). "Myelin protein zero‐like 3 (MPZL3) is a novel protein that can regulate energy homeostasis in preclinical models of obesity." (PMID 33991450, 2021). "Interestingly, we also observed decreased RER indicating that the acute anti‐obesity effects of Mpzl3 ASO were likely due, in part, to increased whole‐body fat oxidation." (PMID 33991450, 2021). "While MPZL3 remains a protein of relatively unknown function, determining its mechanism in energy homeostasis will facilitate development of pharmacological approaches to target obesity and related comorbid conditions." (PMID 33991450, 2021).
ovarian tumors (1 paper, 2025). "Whereas high and low MPZL3-expressing populations are similarly observed in primary ovarian tumors from an independent patient cohort, metastatic omental tumors largely display decreased MPZL3 expression, suggesting that MPZL3 loss is associated with metastatic progression." (PMID 40631617, 2025). "Similar to TCGA data, primary ovarian tumors were comprised of both high- and low-expressing populations, whereas the majority of omental tumors, which represents a major site of metastasis, displayed decreased MPZL3 expression, suggesting that a loss of MPZL3 is associated with tumor progression." (PMID 40631617, 2025). "In addition, MPZL3 transcript expression was negatively associated with gene methylation status, suggesting that CNAs and epigenetic mechanisms contribute to downregulation of MPZL3 in ovarian tumors." (PMID 40631617, 2025). "Our limited in-house patient specimen data suggest that MPZL3 expression is highly heterogeneous in ovarian tumors, whereas omental tumors display primarily decreased expression." (PMID 40631617, 2025).
renal cell carcinoma (1 paper, 2022). "KEGG enrichment analysis showed that high MPZL3 expression was mainly associated with renal cell carcinoma, the neurotrophin signaling pathway and the vasopressin-regulated water pathway." (PMID 35965540, 2022).
seborrheic dermatitis (1 paper, 2022). A chronic, inflammatory skin disorder that affects the scalp, central face and skin folds; it is characterized by scaling and itching. "In seborrheic dermatitis-like lesions of MPZL3-knockout mice, IL17 was more highly expressed in γδ T cells to mediate the pathogenesis of seborrheic dermatitis-like skin inflammation." (PMID 35965540, 2022).
uveal melanoma (1 paper, 2022). A melanoma derived from melanocytes of the uveal tract. "The highest alteration frequency of MPZL3 (alteration frequency > 3%) appeared in UCEC patients with “mutations” as the primary type, and the “deep deletion” mutation of MPZL3 was the main mutation type in uveal melanoma." (PMID 35965540, 2022).